RGS6 (regulator of G protein signaling 6)
Diseases named in the same sentence as RGS6 in open-access papers (continued):
Sharing a sentence is not in itself a finding about the gene and the disease.
tumor (15 papers, 2016 to 2025). "Loss or inactivation of either EGR3 or RGS6 correlates with a more aggressive tumor cell phenotype in multiple cancers, including GBM." (PMID 39796709, 2024). "More commonly, RGS6 is regarded as an important target to modulate cancer risk in a variety of tumor types." (PMID 38066447, 2023). "But the mechanisms underlying these tumor-suppressing functions of RGS6 are not fully understood." (PMID 35902557, 2022). "Moreover, RGS5 deficiency has been reported to be associated with tumor progression in lung cancer, while RGS6 exerts its tumor suppressor function via G protein-independent signaling mechanisms in breast cancer." (PMID 35498542, 2022). "Association mapping of the chromosome 12 locus localized its effect to a region encompassing ∼18 genes, including DRAGO/Susd6, a DNA damage-responsive tumor suppressor and Rgs6, a regulator of G-protein signaling." (PMID 40326784, 2025). "Decreased RGS6 expression was closely correlated with increased tumor size, TNM stage and lymphatic and distant metastasis." (PMID 38066447, 2023). "Our study discovers a novel anti-tumor action of RGS6 in suppressing TGF-β-induced EMT of NSCLC cells." (PMID 35902557, 2022). "Some members of the RGS protein family, including RGS6, have been shown to exhibit tumor-suppressing effects." (PMID 35902557, 2022). "Surprisingly, in tumor tissues, RGS6 expression was downregulated in both the tumor cells and the stromal cells." (PMID 35902557, 2022). "In another study, utilizing Rgs6−/− mice, the role for RGS6 as a tumor suppressor was reported as they displayed accelerated pathological lesions than Rgs6+/+ mice." (PMID 28915710, 2017). "Utilizing RGS6−/− mice we interrogated a possible role for RGS6 as a tumor suppressor using the BBN-induced bladder carcinogenesis model that closely recapitulates human disease." (PMID 27713144, 2016). "This study identifies RGS6, a protein linked to reduced UBC risk among smokers, as a novel and critically important tumor suppressor in bladder using a smoke carcinogen model of UBC in mice that closely recapitulates human disease." (PMID 27713144, 2016). "A deeper analysis revealed upregulation of genes involved in tumor suppression (Clca2, Spink5, Igfbp6, Nptx1, Bex4, Gadd45g, Yipf5), immune regulation (IL6ra, Ccl6, Cd81, Cd244a, Cd151, and Gata4), apoptosis, and pyroptosis (Ddit3, Rgs6, and Gsdmsc2/3/4)." (PMID 39946195, 2025). "Our study suggests that NSCLC could be a useful system to investigate the role of RGS6 in tumor angiogenesis, which may have great impact on our understanding of the function of RGS6 in cancer development and its clinical application." (PMID 35902557, 2022). "This work not only provides new insights into our understanding of the dephosphorylation events in TGF-β signaling and expands our knowledge of anti-tumor signaling actions of RGS6, but also provide solid evidence supporting RGS6 as a prognostic marker and a potential novel target for NSCLC therapy." (PMID 35902557, 2022). "Since then, more and more anti-tumor actions of RGS6 have been discovered." (PMID 35902557, 2022). "Based on the dramatic changes of the histological structures in the tumor tissue, one possibility is that changes in the micro-environments in the tumor tissue induced by tumor cells result in downregulation of RGS6 not only in the tumor cells but also in the stromal cells." (PMID 35902557, 2022).
tumor (continued). "Whether or not this difference between LUAD and LUSC patients reflects different levels of RGS6 expression between LUAD tumor tissues and LUSC tumor tissues is worthy of further study." (PMID 35902557, 2022). "This human patient data demonstrates that there is a reciprocal relationship between RGS6 expression and the presence/risk of UBC as might be expected if RGS6 functions as a tumor suppressor." (PMID 27713144, 2016). "Either drug alone or in combination protected RGS6−/− mice from BBN-induced tumor formation." (PMID 27713144, 2016). "To determine whether RGS6−/− mice could be used to interrogate the tumor suppressor role of RGS6 in bladder, we first characterized RGS6 expression in the mouse bladder." (PMID 27713144, 2016). "Since IHC staining of all 75 paired tumor and normal tissues was performed on the same chip, the difference of RGS6 immunostaining between the tumor tissues and the normal tissues could not be caused by differential staining of these tissues." (PMID 35902557, 2022). "Interestingly, BBN exposure does not completely ablate urothelial RGS6 expression in RGS6+/+ mice, which could be the reason that tumor development is delayed for up to 8 wks in RGS6+/+ mice as compared to RGS6−/− mice." (PMID 27713144, 2016). "Potential tumor suppressor genes GAS7, RGS6, ADAM11 and FBXL2 are up-regulated in the lesser aggressive group L." (PMID 29844869, 2018). "Our next step was to generate a tumor xenografts and metastasis model to further examine the negative effect of RGS6 on NSCLC metastasis." (PMID 35902557, 2022). "Like the mRNA levels, the overall protein levels of RGS6 in tumor tissues were significantly reduced compared to normal tissues." (PMID 35902557, 2022). "The tumor suppressor actions of RGS6 described here are not likely due to alterations in Ras expression or signaling in the bladder urothelium." (PMID 27713144, 2016). "Together, our data identify RGS6 as a master tumor suppressor modulating two critical signaling pathways that are often dysregulated in UBC; therefore, RGS6 represents a potential novel biomarker for UBC diagnosis/prognosis and an appealing new target in its treatment." (PMID 27713144, 2016). "Given our evidence that RGS6 functions as a master tumor suppressor modulating two critical signaling pathways that are often dysregulated in UBC, RGS6 represents a potential novel biomarker for UBC diagnosis/prognosis as well as an appealing new target in its treatment." (PMID 27713144, 2016). "Notably, tumor-suppressive roles have been reported for CAMK2B, EGR3, NPAS2, PCDH8, and RGS6." (PMID 39796709, 2024). "However this trend was not shown when we analyzed mRNA levels of RGS6 in tumor tissues from NSCLC patients, probably due to limited number of samples." (PMID 35902557, 2022). "Thus while BBN-induced increases in Ras expression in bladder wall may contribute to UBC development, the tumor suppressor actions of RGS6 are not involved in this signaling pathway." (PMID 27713144, 2016).
cancer (8 papers, 2016 to 2024). A tumor composed of atypical neoplastic, often pleomorphic cells that invade other tissues. "Besides its ability to induce apoptosis, RGS6 inhibits oncogenic transformation induced by Ras, one of the most important oncogenic proteins mutated in over 30% human cancers, by promoting TIP60-mediated degradation of another oncogenic protein DNMT1." (PMID 35902557, 2022). "Previous investigations show that RGS6 can prevent cell growth or induce apoptosis in cancer cell lines." (PMID 35902557, 2022). "RGS6 induces cell cycle arrest and apoptosis of cancer cells." (PMID 35902557, 2022). "In addition, RGS6 also plays a critical role in cancer biology through G protein-independent mechanisms." (PMID 27713144, 2016). "The mechanism regulating RGS6 expression during cancer development remains unclear." (PMID 35902557, 2022). "The RGS6 structural domain is responsible for the GAP activity of RGS6 and other RGS proteins and allows it to negatively regulate the Gαi/o protein subunit, which is specifically involved in the development and progression of many cancer types." (PMID 37924113, 2023). "This unexpected result indicates that the action of RGS6 was independent of its ability to interact with G protein and suggests that there are uncharacterized signaling activities mediated by the Gα-independent regulation for some RGS proteins, especially in cancer cells." (PMID 27105500, 2016).
psychiatric disorder (4 papers, 2022 to 2025). A disorder characterized by behavioral and/or psychological abnormalities, often accompanied by physical symptoms. "We demonstrate that RGS6 is most highly expressed in CNS, characterize the predominant isoforms, and identify a brain-specific RGS6 protein highly expressed in brain regions associated with various psychiatric disorders." (PMID 34880111, 2022). "A metanalysis identified regulator of G-protein signaling 6 (RGS6) as one of 23 loci with pleiotropic effects on four or more human psychiatric disorders." (PMID 34880111, 2022).
heart (1 paper, 2025). "Contrary to that conclusion, RGS6 was found to confer cardio-protection against ischemic injury, whereas Rgs6 deletion potentiated ischemic heart injury." (PMID 39772618, 2025).
neurodegenerative disease (1 paper, 2014). A disorder of the central nervous system characterized by gradual and progressive loss of neural tissue and neurologic function. "We then characterized degenerating mDA neurons in Rgs6−/− mice for the presence of pathologocial markers observed in PD and in other neurodegenerative diseases." (PMID 25501001, 2014).
neurodevelopmental disorder (1 paper, 2025). A behavioral and cognitive disorder with onset during the developmental period that involves impaired or aberrant development of intellectual, motor, or social functions. "Among the DEGs, strong evidence of involvement in neurodevelopmental disorders was reported for 15 of them (“definitive” gene list from SysNDD, e.g., PLP1, RGS6, and SCN3A) and moderate evidence for 10 more (“limited” gene list from SysNDD, e.g., UNC13A, NMNAT2, and CHL1)." (PMID 40182141, 2025).
RGS6 also shares sentences with these, for which no sentence is quoted: bipolar disorder (3 papers); autism (1); autism spectrum disorder (1); AV block (1); Brugada syndrome (1); cardiovascular disease (1); coronary artery disease (1); heart disease (1); hepatocellular carcinoma (1); ischemia (1); leukemia (1); lung adenocarcinoma (1); lung squamous cell carcinoma (1); pancreatic cancer (1); Parkinson’s (1); prostate carcinoma (1); spinal cord injury (1); squamous cell carcinoma (1).